GIP (gastric inhibitory polypeptide)
Diseases named in the same sentence as GIP in open-access papers (continued):
Sharing a sentence is not in itself a finding about the gene and the disease.
fibrosis (1 paper, 2025). the formation of excess fibrous connective tissue in an organ or tissue in a reparative or reactive process. "Tirzepatide, a co-agonist of glucose-dependent insulinotropic polypeptide (GIP) and GLP-1 receptors already approved in some countries as an antidiabetic and antiobesity agent, has also been assessed to treat individuals with MASH and fibrosis F2-F3." (PMID 41346429, 2025).
gastric cancer (1 paper, 2017). A primary or metastatic malignant neoplasm involving the stomach. "Considering that the postoperative GIP levels were higher than the preoperative levels, GIP secretion seems to be stimulated by gastric cancer surgery." (PMID 29216250, 2017).
gastrointestinal infections (1 paper, 2021). "Results showed that QIAstat-Dx GIP significantly expanded aetiological diagnosis of gastrointestinal infections compared to conventional microbiological methods while orientating a more judicious use of antimicrobial drugs in hospitalised children." (PMID 33963926, 2021).
Headache (1 paper, 2025). Cephalgia, or pain sensed in various parts of the head, not confined to the area of distribution of any nerve. "In addition, there was a near‐significant trend toward a reduced risk of headache with GLP‐1 or GIP/GLP‐1 RA treatment (RR: 0.61; 95% CI: 0.34 to 1.07; p = 0.08; 2 studies; I2 = 93%; p for Cochran's Q < 0.01)." (PMID 40937960, 2025). "In this systematic review and meta‐analysis, treatment with GLP‐1 or dual GIP/GLP‐1 RAs was associated with a significantly reduced risk of papilledema and visual disturbances or blindness, and with a near‐significant reduction in headache risk compared with standard‐of‐care IIH treatment." (PMID 40937960, 2025).
Hypercalcemia (1 paper, 2025). An abnormally increased calcium concentration in the blood. "Another strategy would be to discontinue thiazide diuretics in any patient who is at risk of hypercalcemia before starting GLP-1 and GIP agonists." (PMID 40911613, 2025). "Second, there should be close monitoring of calcium levels in patients starting GIP and GLP-1 agonists, especially in patient populations such as CKD patients or patients on HCTZ who are already susceptible to hypercalcemia." (PMID 40911613, 2025).
hyperlipidemia (1 paper, 2023).
Hypoinsulinemia (1 paper, 2026). A decreased concentration of insulin in the blood. "It has been reported that GIP may promote adipogenesis under hyperinsulinemic conditions and exhibit lipolytic effects under hypoinsulinemia." (PMID 41528263, 2026).
ileus (1 paper, 2025). Decrease in peristalsis in the absence of a mechanical bowel obstruction. "It underscores the diagnostic challenges in differentiating complications such as postoperative ileus, small bowel obstruction, and GLP-1 and GIP agonists effects, given overlapping symptoms like nausea, vomiting, and abdominal distention." (PMID 39917093, 2025).
infarction (1 paper, 2016). A localised pathological necrosis of tissue resulting from obstruction of the blood supply usually by a thrombus, an embolus, or vascular torsion. "In the present study, we demonstrated for the first time that infarction was associated with an increased resistin expression via the GIP-dependent pathway, subsequently leading to an increased NGF expression both in vivo and ex vivo." (PMID 26811539, 2016).
influenza (1 paper, 2025). An acute viral infection of the respiratory tract, occurring in isolated cases, in epidemics, or in pandemics; it is caused by serologically different strains of viruses (influenzaviruses) designated A, B, and C, has a 3-day incubation period, and usually lasts for 3 to 10 days. "For example, higher outdoor temperature was associated with higher SPINK6 levels (maintaining skin homeostasis and restricting influenza activation), and shorter fasting time was associated with higher GIP levels (stimulating insulin secretion)." (PMID 41071435, 2025).
intestinal obstruction (1 paper, 2024). Blockage of the normal flow of the intestinal contents within the bowel. "A number of case reports have linked the use of GLP-1RAs, and the dual GIP-/GLP-1 receptor agonist tirzepatide, to bowel obstruction or ileus." (PMID 39568409, 2024). "However, in these studies, use of DPP-4 inhibitors was, in general, associated with a higher risk of intestinal obstruction than GLP-1RAs, which is surprising given the minimal effect of GIP on gastric emptying and the marginally elevated GLP-1 concentrations observed." (PMID 39568409, 2024).
iron deficiency (1 paper, 2025). "We found GiP to be associated with lower ferritin concentrations and iron deficiency in pre-pregnancy and in every trimester." (PMID 40038683, 2025). "This study found an association between GiP and iron deficiency before pregnancy." (PMID 40038683, 2025). "On average, women with GiP in any trimester had significantly lower ferritin (p = 0.001) and had a greater proportion with iron deficiency at pre-pregnancy (p = 0.022) compared to women without GiP." (PMID 40038683, 2025).
ischemic stroke (1 paper, 2024). A stroke disorder caused by obstruction of blood flow to the brain, due to thrombotic (local blood clot formation) or embolic (due to a blood clot or other material traveling from another site) event. "Despite an association of genetically proxied GIP/GIPR agonism with a favorable cardiometabolic risk profile (including higher BMI and HDL cholesterol), there was no strong evidence of association with ischemic stroke risk." (PMID 39628323, 2024).
Lipedema (1 paper, 2025). Disorder of adipose tissue characterized by symmetric and bilateral enlargement of the lower extremities due to abnormal deposition of subcutaneous fat often in obese women. "Given its dual GLP-1/GIP agonism, tirzepatide emerges as the most plausible pharmacological candidate capable of interrupting the pathogenic cycle of lipedema and potentially modifying the natural history of the disease." (PMID 41226777, 2025). "This context-dependent reprogramming explains why tirzepatide, unlike isolated GIP exposure, produces net reductions in subcutaneous and visceral fat even in insulin-sensitive phenotypes such as early-stage lipedema." (PMID 41226777, 2025).
lymphedema (1 paper, 2025). Excess fluid collection in tissues, causing swelling. "The new focus on GLP-1 agonists raises the possibility that GLP-1/GIP agonists may reduce tumor progression and associated lymphedema, although these effects are still under investigation." (PMID 40713647, 2025).
MODY (1 paper, 2025). "Here we share our own experience using GLP-1 RA and dual GIP/GLP-1 RA therapy in genetically confirmed MODY, with a focus on glycaemic control, weight, and the potential to reduce or stop sulfonylureas and insulin." (PMID 41262822, 2025). "We conducted a retrospective case series at Tawam Hospital (2019-2024), including patients with genetically confirmed MODY who received a Glucagon-like peptide-1 (GLP-1) receptor agonist or dual GLP-1/Glucose-dependent insulinotropic polypeptide (GIP) receptor agonist for at least three months." (PMID 41262822, 2025). "GLP-1 receptor agonists and dual GIP/GLP-1 receptor agonists improved glycaemic control, reduced body weight, and decreased insulin dependency in MODY patients." (PMID 41262822, 2025). "In conclusion, our experience adds to a growing body of evidence that GLP-1 RAs and dual GIP/GLP-1 RAs can be safe and effective in selected MODY patients." (PMID 41262822, 2025).
morbid obesity (1 paper, 2023). An excess of body weight, normally defined as an individual with a body mass index greater than 35 or a body weight greater than one hundred percent of ideal body weight. "Apart from that, GIP levels seemed to be slightly, but non-significantly, decreased in patients with morbid obesity compared to the CTRL and were not affected by bariatric surgery." (PMID 37266430, 2023).
neutropenia (1 paper, 2017). A decrease in the number of neutrophils found in the blood. "The three groups of treatment were similar regarding other AEs such as proteinuria of grade 3 or greater, GIP or fistula, neutropenia of grade 4 and febrile neutropenia, venous or arterial thrombosis, and wound disruption." (PMID 27852039, 2017). "The most common ones were the following: neutropenia (12.2%), GIP (7.1%) hemorrhage (23.5%)." (PMID 27852039, 2017).
osteosarcoma (1 paper, 2024). A usually aggressive malignant bone-forming mesenchymal neoplasm, predominantly affecting adolescents and young adults. "Exposing three human osteosarcoma cell lines expressing GIPRs (TE-85, MG-63, and Saos-2) to GIP resulted in the release of bone formation marker P1NP, in which the expression of Col-1 in Saos-2 cells increased." (PMID 38725663, 2024).
ovarian carcinoma (1 paper, 2017). A malignant neoplasm originating from the surface ovarian epithelium. "Insulin, GIP, and PP were only measured in the NHL and ovarian cancer studies; Spearman correlation coefficients were calculated for the three markers by study." (PMID 28753646, 2017). "Insulin and PP were weakly correlated (0.2 for the NHL and ovarian cancer studies); however, GIP was moderately correlated with insulin (0.5 for the NHL and ovarian cancer studies) and weakly correlated with PP (0.3 for the NHL study and 0.4 for the ovarian cancer study)." (PMID 28753646, 2017).
pancreatic cancer (1 paper, 2024). "These SPNs were modified with DOTA for complexing 177Lu and with glucose-dependent insulinotropic polypeptide (GIP) for targeting pancreatic cancer." (PMID 38703297, 2024).
pancreatitis (1 paper, 2025). Inflammation of the pancreas. "Consistent with glucose-stimulated defects in GIP responsiveness, individuals with pancreatitis show higher levels of blood glucose relative to healthy controls, and fail to appropriately increase plasma insulin levels after oral glucose challenge despite rapid elevation of IR-GIP." (PMID 40024571, 2025).
papilledema (1 paper, 2025). "GLP‐1 and dual GIP/GLP‐1 RAs are associated with a significantly lower risk of papilledema and visual disturbances or blindness and a lower headache risk compared with standard‐of‐care." (PMID 40937960, 2025).
renal carcinoma (1 paper, 2023). A carcinoma arising from the epithelium of the renal parenchyma or the renal pelvis. "In colocalization analysis, there was little evidence to support one or more shared causal variants for fasting or 2-h GIP concentrations and renal cancer risk in GIPR (H4<21.2%)." (PMID 37250804, 2023).
renal dysfunction (1 paper, 2023). "An increase in the level of GIP was associated with an increased chance of having renal dysfunction by 1.1%." (PMID 37623488, 2023). "The concentrations of adipsin, ghrelin, GIP, and PYY were 1.2 times greater in the group of individuals with renal dysfunction." (PMID 37623488, 2023).
Sepsis (1 paper, 2019). Sepsis is defined as life-threatening organ dysfunction caused by a dysregulated host response to infection. "In support of this hypothesis, we recently found that foals with severe sepsis tend to have lower insulin and GIP concentrations (L.M.R./R.E.T., personal communication)." (PMID 31664736, 2019).
short bowel syndrome (1 paper, 2025). "Production of GIP in short bowel syndrome has not been studied yet." (PMID 40886373, 2025).
metabolic disorders (27 papers, 2015 to 2026). "Taken together, these findings indicate that while the insulinotropic effects of GIP are blunted in metabolic disease, its skeletal antiresorptive action is preserved." (PMID 41596254, 2026). "Pharmacological treatments such as GLP-1 receptor agonists and dual GLP-1/GIP agonists, extensively studied in metabolic diseases, offer hope for renoprotection." (PMID 41156559, 2025). "This has implications for a broad spectrum of metabolic disorders, particularly since dual agonism can prevent glycaemic volatility and safeguard against hypoglycaemia via GIP’s differential action on α cells." (PMID 37900147, 2023). "Plasma hormone peptides, including GLP-1, GIP, Glucagon, and OXM, possess multiple physiological roles and potential therapeutic and diagnostic utility as biomarkers in the research of metabolic disorders." (PMID 26222180, 2015). "GIP, an incretin promoter of postprandial insulin secretion alongside GLP-1 has been frequently implicated in glucose homeostasis and is being leveraged for the treatment of metabolic disease." (PMID 38762719, 2024). "As shown in our study, WA has the potential to reduce factors relating to the development of metabolic disorders, such as higher glucose and GIP responses during the night, through consumption in an evening meal, so WA can be expected to rearrange disordered circadian rhythms." (PMID 30658460, 2019). "Moreover, exogenous GIP or its analogs may confer protective effects in other metabolic disorders accompanied by bone deterioration—such as chronic kidney disease or Cushing’s syndrome—which merits further investigation." (PMID 41596254, 2026). "Gut-pancreatic peptides such as glucose-dependent insulinotropic polypeptide (GIP), glucagon, amylin, and peptide YY (PYY) are of particular interest due to their distinct pharmacological benefits and therapeutic promise in metabolic disorders." (PMID 42307179, 2026). "For research purposes, multiple GIP analogs that resist DPP-4 degradation have been synthesized, including N-AcGIP, Pro3GIP, and D-Ala2-GIP to study various metabolic diseases." (PMID 38725663, 2024).
cardiovascular disease (19 papers, 2010 to 2025). "It was proved that functional variant SNPs in GIP gene were associated with cardiovascular disease in a small-scale case-control study." (PMID 28840129, 2017). "An earlier study in European population looked at the role of common variants in GIPR and GIP with cardiovascular diseases." (PMID 20673334, 2010). "To examine relationships between incretin hormones and MetS components, we measured circulating levels of incretins, GLP-1 and gastric inhibitory polypeptide (GIP), in high-risk patients for cardiovascular disease." (PMID 20470376, 2010). "Our study aimed to investigate whether the polymorphisms in GIP genes could affect the risk of cardiovascular disease in type 2 diabetic patients in the Chinese Han population." (PMID 29765988, 2018). "The role of GIP in cardiovascular disease is yet to be clarified; pharmacological doses of GIP-Receptor agonists (GIP-RA) have been found to exert antiobesity effects in animal models." (PMID 33924893, 2021). "We hypothesised that GIP has untoward effects on cardiovascular biology, in contrast to glucagon-like peptide 1 (GLP-1), and therefore investigated the effects of GIP and GLP-1 concentrations on cardiovascular disease (CVD) and mortality risk." (PMID 31974732, 2020). "However, the role of GIP in cardiovascular disease remains to be elucidated." (PMID 32098413, 2020). "Tirzepatide, a dual GIP and GLP-1 receptor agonist, has the potential to revolutionize the management of metabolic and cardiovascular diseases." (PMID 41405657, 2025). "Data from our laboratory demonstrated that fasting GIP concentrations were significantly higher in individuals with a history of cardiovascular disease (CVD) than in those without, and that GIP receptor (GIPR) gene mRNA expression is higher in the arterial wall of individuals with symptoms of CVD." (PMID 31974732, 2020).
cancer (14 papers, 2011 to 2025). A tumor composed of atypical neoplastic, often pleomorphic cells that invade other tissues. "GIP has been implicated in processes such as cell proliferation and differentiation, which may stimulate the growth of certain cancers." (PMID 40282969, 2025). "In addition, higher endogenous fasting GLP-1 levels were found to be associated with lower risk of any incident first cancer, whereas both fasting glucose and GIP-levels were marginally significantly associated with increased risk of incident cancer risk when adjusted for age and sex." (PMID 36611045, 2023). "Participants who suffered from any incident first cancer (n = 485) were younger, more often male, with higher waist circumference and lower post-challenge GIP levels." (PMID 36611045, 2023). "It has been determined that a time exposure of GIP-34 treatment was critical in order to accomplish growth cessation of cancer cells." (PMID 24212829, 2011). "In other reports, both GIP segments were found effective as anti-angiogenic factors during chick development and in mouse cancer cell cultures." (PMID 24212829, 2011). "The GIP-8 segment (also called AFPep, P149c, P447, P472-2) is an 8-amino acid peptide first reported by the author (GJM) in 1995 as an anti-cancer and anti-growth fragment derived from the 34-mer GIP segment." (PMID 24212829, 2011). "A trypsin digest of the GIP-34 peptide yielded an 8–9 amino acid fragment which was found to possess the E-dependent anti-cancer growth properties of the original 34-mer peptide." (PMID 24212829, 2011). "This discrepancy might be explained in terms of comparing the effects of metabolic signaling along the GIP/GIPR axis with the pathological conditions of a cancer cell line." (PMID 38730608, 2024). "Herein, we explored whether endogenous circulating GIP and GLP-1 levels are associated with incident first cancer(s) in the population-based Malmö Diet and Cancer Study." (PMID 36611045, 2023). "Here, we explored whether fasting and oral glucose tolerance test post-challenge glucose-dependent insulinotropic peptide (GIP) and GLP-1 levels were associated with incident first cancer." (PMID 36611045, 2023). "Thus, in cell culture studies, GIP-34 treatment of cancer cells should be maintained for at least eight days with alternate day treatment of the 34-mer peptide to achieve continued peptide exposure to the cells." (PMID 24212829, 2011). "In both instances, the anti-cancer effect of GIP combined or conjugated to the chemotherapy drug was enhanced in T47D breast cancer and glioblastoma cells; furthermore, it may be possible that drug resistance to chemoagents could be bypassed." (PMID 24212829, 2011). "In that collaborative report, it corroborated the observation that radiolabeled GIP-34 could bind to cancer cells being localized in rodent mammary tumors in vivo at 24 h post-IV-injection." (PMID 24212829, 2011). "However, we noticed a change in the MQI among women with cancer and obese women with and without cancer, which was linked to high levels of C-peptide, glucagon, and gastrointestinal incretins (GIP and GLP-1)." (PMID 38397883, 2024). "Thus, the initial goal of the GIP technology platform was to eventually make GIP-34 and its growth inhibitory subcomponents available as peptide drugs for adults afflicted with benign hyperplasia and cancer growth as seen in hepatic, reproductive, and gastrointestinal tumors." (PMID 24212829, 2011). "The GIP-DOX conjugate exhibited cytotoxic efficacy that matched DOX alone, showed specificity for binding to cancer cells, and enhanced peptide/DOX delivery across cancer cell membranes and into the cytoplasm." (PMID 24212829, 2011). "Due to the low nanogram levels (6 ng/mL) present in circulating adult HAFP, transformed AFP and its exposed GIP segments are not available to adult humans to aid in bodily defense from cancer and benign growths." (PMID 24212829, 2011).